FGF21 (fibroblast growth factor 21)
Diseases named in the same sentence as FGF21 in open-access papers (continued):
Sharing a sentence is not in itself a finding about the gene and the disease.
endothelial dysfunction (11 papers, 2014 to 2024). In vascular diseases, endothelial dysfunction is a systemic pathological state of the endothelium (the inner lining of blood vessels) and can be broadly defined as an imbalance between vasodilating and vasoconstricting substances produced by (or acting on) the endothelium. "Fibroblast growth factor-21 (FGF-21) is upregulated in DR as a compensatory response to endothelial dysfunction that aims to repair retinal microvascular lesions." (PMID 37092467, 2023). "FGF21 administration reverses endothelial dysfunction under oxidative stress in Apoe−/− mice and improves endothelial progenitor cell functions via the AKT/eNOS/NO pathway." (PMID 37894840, 2023). "OSM, MCP‐2, TGF‐α, and CXCL6 are likely to have an association with endothelial dysfunction and some are mostly or additionally involved in IR (MCP‐1, FGF‐21, TRAIL, and ADA) or insulin metabolism (TNFSF14/LIGHT)." (PMID 36467791, 2022). "We therefore designed this study to investigate the effects of FGF21 on cultured EPCs under H2O2‐induced high oxidative stress conditions and assess the potential impact of FGF21 on endothelial dysfunction in hypercholesterolaemic mice." (PMID 35307922, 2022). "To validate the role of AMPK in FGF21-mediated alleviation of endothelial dysfunction induced by HG, we used AMPKα siRNA to knockdown its expressions in human umbilical vascular endothelial cells (HUVECs)." (PMID 31511499, 2019). "Increased serum FGF21 may compensate for endothelial dysfunction in retinopathy, with defects in FGF21 expression or activation reducing insulin sensitivity, liver fatty acid oxidation, and triglyceride clearance." (PMID 39687000, 2024). "First, FGF21 can alleviate endothelial dysfunction via multiple pathways." (PMID 36594101, 2023). "Similarly, FGF21 can improve endothelial dysfunction in type 1 diabetes, and the molecular mechanism involves AMPK activation." (PMID 37894840, 2023). "Notably, FGF21 can promote the secretion of adiponectin, which also exerts an atheroprotective effect by reducing endothelial dysfunction, thereby blocking the conversion of macrophages to foam cells and inhibiting vascular smooth muscle cell proliferation." (PMID 36594101, 2023). "FGF21-induced activation of the CaMKK2-AMPKα signaling pathway suppresses oxidative stress and enhances endothelium-dependent vasorelaxation of the aorta, thus alleviating endothelial dysfunction." (PMID 36213282, 2022). "Taken together, these data suggest that FGF21 may ameliorate endothelial dysfunction in diabetic mice via AMPKα-mediated inhibition of local oxidative stress in mouse aorta." (PMID 31511499, 2019). "The data suggest that FGF21 may activate AMPKα to suppress oxidative stress and alleviate endothelial dysfunction." (PMID 31511499, 2019). "However, the relationship between plasma FGF21 and circulating EPCs and the impact of FGF21 on high‐fat diet (HFD)‐induced endothelial dysfunction remain unclear." (PMID 35307922, 2022). "Nevertheless, it remains unclear as to whether FGF21 ameliorates endothelial dysfunction." (PMID 31511499, 2019). "Therefore, FGF21 induces relaxation of aorta through CaMKK2/AMPKα activation may also contribute to the alleviation of endothelial dysfunction in addition to its potent inhibition on oxidative stress." (PMID 31511499, 2019). "Although FGF21 failed to rescue high blood glucose in T1D, it remained effective in the alleviation of endothelial dysfunction." (PMID 31511499, 2019).
injury (11 papers, 2017 to 2025). Damage inflicted on the body as the direct or indirect result of an external force, with or without disruption of structural continuity. "Overexpression of FGF21 in BMSCs enhanced their homing to injury site in animal model of traumatic brain injury thereby indicating a possible approach for MSC-based therapy in the injury." (PMID 37191410, 2023). "FGF21 has been reported to enhance angiogenesis and migration of human brain microvascular endothelial cells showing its therapeutic potential for treating human brain injury." (PMID 35735915, 2022). "Circulating FGF21 levels were increased in acute and chronic renal dysfunction mice, and recombinant FGF21 also showed therapeutic potential in cisplatin-induced kidney injury." (PMID 36440004, 2022). "Previous studies showed that serum levels of FGF21 are significantly increased in both AKI and CKD, and FGF21 concentration is correlated with the severity of kidney injury." (PMID 32210821, 2020). "Furthermore, previous research has shown that the neuroprotective effect of fibroblast growth factor 21 (FGF21) in promoting neuronal survival and neurofunctional recovery after brain injury is mediated by the activation of PI3K/Akt signaling." (PMID 31680984, 2019). "Therefore, monitoring the elevation of serum FGF21 levels in CHB patients may provide valuable information about tumorigenesis, especially in those without obvious clinical signs of acute liver injury." (PMID 29184085, 2017).
Parkinson disease (11 papers, 2021 to 2025). A progressive degenerative disorder of the central nervous system characterized by loss of dopamine producing neurons in the substantia nigra and the presence of Lewy bodies in the substantia nigra and locus coeruleus. "Here, we aimed to elucidate the actions and the underlying mechanisms of FGF21 on dopaminergic neurodegeneration using cellular models of parkinsonism." (PMID 37910178, 2024). "A hierarchical bioactive hydrogel (OACDP) targeting Parkinson's disease is developed, enabling the asynchronous release of three drugs (caffeic acid, fibroblast growth factor 21, and Edaravone)." (PMID 39630931, 2025). "This impact is underscored by preclinical studies in Parkinson’s, Alzheimer’s and other CNS disease where FGF21 promotes neuroprotection and mitigates neurodegeneration through effects on different cell populations which crossover to ALS." (PMID 40788112, 2025). "Moreover, FGF21 has neuroprotective effects against Parkinson's disease (PD) by promoting the anti‐inflammatory phenotype." (PMID 40172524, 2025). "Moreover, it has been reported that FGF21 protects dopaminergic neurons in Parkinson′s disease models by repressing neuroinflammation." (PMID 36293323, 2022). "Serum growth factors (BDNF, FGF-21, NGF and proNGF), α-synuclein, physical performance and Parkinson’s Disease Fatigue Scale (PFS-16) responses were analyzed to evaluate the pre-post variation and differences among groups." (PMID 36845654, 2023). "The effects of FGF21 on Parkinson's disease (PD) and its relationship with gut microbiota have not been elucidated." (PMID 37334756, 2023).
alcoholic fatty liver disease (10 papers, 2016 to 2026). Lipid infiltration of the hepatic parenchymal cells that is due to alcohol abuse. "Alcoholic fatty liver disease (AFLD), another condition that cause liver injury, significantly increased FGF21 levels as a protective factor; FGF21 can reverse the progression of AFLD and can be a potential therapeutic agent for it." (PMID 36457562, 2022). "First, we showed that circulating FGF21 levels are increased in patients with alcoholic steatohepatitis and that chronic alcohol exposure resulted in an up-regulation of FGF21 expression in mice." (PMID 27498701, 2016). "In addition, FGF21 relieves the oxidative stress of pathological conditions such as alcoholic fatty liver disease that FGF21 pre-incubation or FGF21 injection restored the antioxidant activities of SOD and glutathione peroxidase in ethanol-induced HepG2 cells and alcohol-gavaged mice, respectively." (PMID 33513795, 2021). "Targeting FGF21 signaling could be a novel treatment approach for alcoholic steatohepatitis." (PMID 27498701, 2016). "Therefore, exogenous FGF21 could potentially be used as a treatment for alcoholic fatty liver disease." (PMID 27498701, 2016). "FGF21 protects the liver not only from NAFLD and NASH but also from alcoholic fatty liver disease (AFLD)." (PMID 36457562, 2022). "Fibroblast growth factor 21 (FGF21) acts as a downstream molecule of the PPARα signaling pathway to regulate the liver lipid metabolism and contribute to the CYP2a5 protective effects on alcoholic fatty liver disease." (PMID 34445672, 2021).
anorexia nervosa (10 papers, 2011 to 2025). A disorder most often seen in adolescent females characterized by a refusal to maintain a minimally normal body weight, an intense fear of gaining weight, a disturbance in body image, and, in postmenarcheal females, the development of amenorrhea. "Consistent with the study in women with anorexia nervosa, we found that FGF21 levels were low in AA compared to EA and non athletes and inversely associated with hours per week of exercise, likely again an adaptive response to conserve energy." (PMID 24926783, 2014). "Fibroblast growth factor-21 may be a putative factor of GH resistance in anorexia nervosa." (PMID 23634145, 2013).
Anxiety (10 papers, 2019 to 2023). Intense feelings of nervousness, tension, or panic often arise in response to interpersonal stresses. "Higher FGF-21 levels were associated with a higher mean intensity of headache attacks, reduced health-related life quality and anxiety." (PMID 34572118, 2021). "Regarding quality of life and anxiety, the presence of anxiety symptoms according to HADS-D was associated with lower FGF-21 levels." (PMID 34572118, 2021). "FGF8-deficient mice display increased anxiety-like behavior, while FGF21 administration in rats induces anxiogenic behavior." (PMID 30804785, 2019). "Increased stress and anxiety levels determined by reliable psychometric instruments, in the caregivers of the OB girls had an intriguing relation to the FGF21 levels of the children under their care." (PMID 35740758, 2022). "It is interesting that increased anxiety, depressive symptoms and stress levels of the caregivers, as depicted in all three related questionnaires, had a significant impact on serum FGF21 in children in the OB group only." (PMID 35740758, 2022). "This is partially in line with existing data showing reduced FGF-21 levels in cerebrospinal fluid in patients with anxiety symptoms, although a corresponding connection with depressive symptoms has also been described here." (PMID 34572118, 2021). "As there are no previous studies exploring the possible associations of FGF21 with stress and anxiety or depression indices, this was an exploratory study." (PMID 35740758, 2022). "Anxiety correlates with lower FGF-21 values in migraine patients." (PMID 34572118, 2021). "In addition, FGF8 and FGF21 can also affect anxiety behavior, and they exert their influence in opposite directions." (PMID 30804785, 2019). "However, increasing systemic FGF-21 levels in WT mice did not phenocopy augmented anxiety-like behavior observed in UCP-1 KO mice, and blocking FGF-21 activity in KO mice did not rescue their phenotype." (PMID 36194650, 2022). "Together, our results show that the increase in anxiety observed in UCP-1 KO mice is not induced by enhanced levels of FGF-21 or other direct humoral or neural communicatory signals from BAT to brain, proposing a role for brain-expressed UCP-1 in the regulation of emotional behavior." (PMID 36194650, 2022).
diabetic retinopathy (10 papers, 2014 to 2024). "According to the results of univariate logistic regression model HbA1c, FBS and FGF21 had significant associations with the risk of diabetic retinopathy." (PMID 29285020, 2017). "The number of subjects in the study population was barely adequate to permit clear estimations to be made about the association of serum FGF21 concentrations with the severity of the diabetic retinopathy." (PMID 24895642, 2014). "The association of FGF21 with the severity of diabetic retinopathy may open up future projects on the early detection and prevention of the condition." (PMID 24895642, 2014). "This study shows that the increase in serum concentration of FGF21 was associated with the severity of diabetic retinopathy and suggests that FGF21 may play a role in the pathogenesis of diabetic retinopathy and its degree." (PMID 24895642, 2014). "Previous studies have shown that the level of FGF21 was also upregulated in fundus diseases such as diabetic retinopathy and infarct-related conditions like stroke." (PMID 38789571, 2024). "In type 1 diabetic mice, FGF21 can prevent early diabetic retinopathy by protecting photoreceptor function." (PMID 36594101, 2023). "Previous studies have shown that the serum level of FGF21 correlates with vascular eye diseases such as diabetic retinopathy and retinopathy of prematurity." (PMID 32095207, 2020). "The results of the ROC curve analysis did not provide a threshold concentration of FGF21 for the existence of diabetic retinopathy and thus a predictive value cannot be assigned to FGF21 concentrations in relation to the development of the condition." (PMID 24895642, 2014). "ROC curve analysis was performed in order to establish a threshold FGF21 concentration for the existence of diabetic retinopathy." (PMID 24895642, 2014). "It is like that with larger numbers of patients it would be possible to obtain a threshold for FGF21 concentration that is significant for the development of diabetic retinopathy." (PMID 24895642, 2014). "This is consistent with our previous reports and other studies that PPARα agonists (pemafibrate or fenofibrate) increase serum levels of FGF21 as well as boost liver function to exert therapeutic effects in ischemic retinopathies such as diabetic retinopathy or ocular ischemic syndrome." (PMID 34502311, 2021). "The model was used to evaluate the capability of FGF21 to predict diabetic retinopathy." (PMID 29285020, 2017). "Regression model was used to evaluate the role of FGF21 in predicting diabetic retinopathy." (PMID 29285020, 2017). "Since the association between FGF21 and diabetic retinopathy is not clear, this study was conducted to investigate this relationship." (PMID 29285020, 2017). "However, the mechanisms responsible for the elevation of FGF21 concentration with the progression of diabetic retinopathy are not fully understood." (PMID 24895642, 2014). "To explore the physiological and pathological relevance of FGF21 in patients with diabetic retinopathy, we measured the serum concentrations of FGF21 in Chinese subjects and analyzed its association with a cluster of metabolic parameters that related to the changes seen in retinopathy." (PMID 24895642, 2014). "We speculate that FGF21 might control diabetic retinopathy by modulating the lipid profile." (PMID 36943533, 2023). "Further elucidation of the types of lipids (long chain, short chain, medium chain) modulated by FGF21 is important, because modulation of the lipid supply to prevent ROP (and diabetic retinopathy) is feasible." (PMID 36943533, 2023). "FGF21 protects against several neurovascular retinal disorders including proliferative ROP, retinitis pigmentosa, diabetic retinopathy, retinal vascular leakage, and neovascular age-related macular degeneration." (PMID 36943533, 2023).
diabetic retinopathy (continued). "According to the results of this study, serum levels of FGF21 in diabetic patients was higher than the control group but these raised levels could not predict the presence of diabetic retinopathy." (PMID 29285020, 2017). "However, there is no doubt that the limitations of FGF21 in diabetic retinopathy still need further study and investigation." (PMID 24895642, 2014). "Serum FGF21 concentrations in patients with proliferative diabetic retinopathy or nonproliferative diabetic retinopathy were significantly higher than those in patients without diabetic retinopathy." (PMID 24895642, 2014).
Hypercholesterolemia (10 papers, 2019 to 2025). An increased concentration of cholesterol in the blood. "Our obese rats were characterized by increased calorie consumption and body adiposity, hypercholesterolemia, elevated levels of liver enzymes and FGF-21, while the level of FGF-19 was reduced." (PMID 36362225, 2022). "FGF21 also suppressed cholesterol biosynthesis and attenuated hypercholesterolemia by inhibiting the production of SREBP-2 in hepatocytes." (PMID 32957703, 2020). "Recently it was found that FGF21 serves as a potential negative regulator of PCSK9, which is in line with our observation that hypermethylation of PCSK9 corresponds with higher circulating FGF21 levels in patients with hypercholesterolemia compared to control subjects." (PMID 33028190, 2020).
renal fibrosis (10 papers, 2021 to 2025). A final common manifestation of a wide variety of chronic kidney diseases characterized by glomerulosclerosis and tubulointerstitial fibrosis. "Increased plasma levels of FGF21 following intravenous administration of Ad‐FGF21 led to a reduction in renal fibrosis in mice after UUO." (PMID 39887648, 2025). "FGF21 prevents renal fibrosis by negatively regulating TGF-β/SMad2/3-mediated epithelial-to-mesenchymal transition in the diabetic mouse." (PMID 35369322, 2022). "Above all, it is unquestionable that FGF21 is of extraordinary significance in the prevention and potential treatment of renal fibrosis." (PMID 35677107, 2022). "In addition, systemic administration of Ad‐FGF21 to WT mice significantly reduced renal fibrosis at day 7 after UUO operation compared with Ad‐β‐gal treatment." (PMID 39887648, 2025). "Furthermore, FGF21 overexpression via intravenous plasmid injection attenuated UUO‐induced renal fibrosis and inflammatory responses in mice." (PMID 39887648, 2025). "The emerging protective role of FGF21 in renal fibrosis has been widely acknowledged." (PMID 35677107, 2022). "Some studies suggested that FGF21 could protect against renal fibrosis, which is often found in patients with CKD." (PMID 34918690, 2021). "Some evidence suggests that FGF21 could protect against renal fibrosis, which is often found in patients with CKD." (PMID 34918690, 2021). "FGF21 treatments significantly decreased PDGF, VEGF, and CTGF expression, which conspicuously increased in renal fibrosis, by downregulating the phosphorylation level of STAT5." (PMID 35677107, 2022). "FGF21 can negatively regulate TGF-β1-induced Smad2/3 nuclear translocation, and reduce collagen precipitation and renal fibrosis." (PMID 34830222, 2021). "FGF21 could down-regulate TGF-β1 and induce nuclear translocation of Smad2/3 to reduce collagen precipitation and renal fibrosis." (PMID 34830222, 2021).